MALAT1 (metastasis associated lung adenocarcinoma transcript 1)
Diseases named in the same sentence as MALAT1 in open-access papers (continued):
Sharing a sentence is not in itself a finding about the gene and the disease.
glaucoma (5 papers, 2019 to 2025). Increased pressure in the eyeball due to obstruction of the outflow of aqueous humor. "In contrast, a study focusing on glaucomatous ocular hypertension demonstrated a significant decrease in MALAT1 expression and a notable increase in miR-149-5p expression in a glaucoma model subjected to high-pressure conditions in vitro." (PMID 40128064, 2025). "It was demonstrated that the protective role of MALAT1 in glaucoma patients is played via the PI3K/Akt cascade to reduce the apoptosis of RGCs." (PMID 34599867, 2021). "And studies found that MALAT1 can regulate apoptosis activity of retinal ganglion cells through PI3K/Akt signal in glaucoma." (PMID 31680442, 2020). "In summary, these findings suggest that MALAT1 may offer protective benefits for RGCs in glaucoma in vitro." (PMID 40128064, 2025).
gynecological cancers (5 papers, 2017 to 2023). "It was revealed that lncRNA MALAT1 was correlated with gynecological cancers." (PMID 35517413, 2022). "We further provide various perspectives on the association of some lncRNAs, i.e., HOTAIR, NEAT1, H19, MALAT1, and MEG3, in terms of invasion, proliferation, metastasis, apoptosis, and drug resistance of breast and gynecological cancers based on recent discoveries." (PMID 34885213, 2021). "Therefore, in this article, we highlight the role of various lncRNAs and specifically five lncRNAs—HOTAIR, NEAT1, H19, MALAT1, and MEG3—in cancers unique to women, including breast and gynecological cancers." (PMID 34885213, 2021). "In this article, we present a summary of the progress on ascertaining the biological functions of five lncRNAs (HOTAIR, NEAT1, H19, MALAT1, and MEG3) in female-oriented cancers, including breast and gynecological cancers, with the perspective of carcinogenesis, cancer proliferation, and metastasis." (PMID 34885213, 2021).
heart failure (5 papers, 2021 to 2025). Inability of the heart to pump blood at an adequate rate to meet tissue metabolic requirements. "In addition to MALAT1, our multivariate analysis identified the other four variables (ALI/ARDS, heart failure, mechanical ventilation, and bacteria) that were independently associated with increased risk of mortality." (PMID 39061025, 2024).
HIV-1 infection (5 papers, 2019 to 2025). The type species of lentivirus and the etiologic agent of acquired immunodeficiency syndrome (AIDS). "Taken together, these results demonstrate that MALAT1 expression is up-regulated upon HIV-1 infection." (PMID 30788509, 2019). "In this study, we discovered that lncRNA MALAT1 expression is required for efficient HIV-1 infection." (PMID 30788509, 2019). "To further confirm the role of MALAT1 in HIV-1 infection, we overexpressed it by transfecting the pcDNA3.1/MALAT1 into PHA-P-activated primary CD4+ T cells, and then infected these cells with HIV-Luc/NL4-3." (PMID 30788509, 2019). "Taken together, these results demonstrate that MALAT1 promotes HIV-1 infection." (PMID 30788509, 2019). "To confirm that the up-regulation of MALAT1 upon HIV-1 infection is universal, we also used PHA-P-activated primary CD4+ T cells, CD4+ T-lymphocyte cell line Hut/CCR5, Jurkat and H9 cells for infection with either pseudotyped HIV-Luc/NL4-3 or replication competent HIV-1/NL4-3." (PMID 30788509, 2019). "Results showed that the MALAT1 knockout significantly impaired HIV-1 infection." (PMID 30788509, 2019). "Results showed that MALAT1 knockdown significantly reduced viral particles released into the supernatant as quantified by p24Gag production; in parallel, the expression of HIV-1 gag mRNA was also significantly reduced, confirming MALAT1 is required for optimal HIV-1 infection and replication." (PMID 30788509, 2019). "Whether MALAT1 could be a biomarker in HIV-1 infection is an interesting topic for future studies." (PMID 30788509, 2019). "The interplay between MALAT1 and ETS1 has not been previously reported for HIV-1 infection, and we propose that this represents a novel indirect mechanism of HIV-1 regulation by ETS1." (PMID 40198713, 2025).
Myocardial fibrosis (5 papers, 2019 to 2025). "Moreover, HE staining and Masson staining of myocardial tissues demonstrated that lncRNA MALAT1 over-expression led to more severe myocardial fibrosis and more hypertrophic myocardial cells, which were opposite to the trend caused by lncRNA MALAT1 silencing." (PMID 31619581, 2019). "Over-expression of lncRNA MALAT1 caused severe myocardial fibrosis in SHRs." (PMID 31619581, 2019). "Moreover, we also found that over-expression of lncRNA MALAT1 promoted cell proliferation, myocardial fibrosis, and cell cycle entry by inhibiting the transcription of MyoD." (PMID 31619581, 2019). "MALAT1 knockout can reduce cell proliferation, collagen production, and inhibit the activation of TGF- β1 induced by MI or angiotensin I, so as to reduce myocardial fibrosis and improve myocardial remodeling." (PMID 33952724, 2021). "In summary, Malat1 is upregulated in DCM, and MALAT1 knockdown can decrease myocardial fibrosis, inflammation, and apoptosis to improves DCM." (PMID 33889601, 2021). "Moreover, the myocardial tissues of rats were analyzed using HE staining and Masson staining and the results showed that myocardial fibrosis and myocardial cell hypertrophy were both attenuated in response to over-expression of MyoD, which could reverse the enhancing role of lncRNA MALAT1." (PMID 31619581, 2019). "LncRNA MALAT1 could regulate the activity of TGF- β1 through microRNA-145, and promote myocardial fibrosis and worsen cardiac function after MI." (PMID 33952724, 2021).
ovarian tumor (5 papers, 2014 to 2025). "In ovarian tumor, the inhibition of MALAT1 has significantly impeded EMT-related genes." (PMID 40149594, 2025). "The present study found that MALAT-1 is highly expressed in ovarian tumors." (PMID 27227769, 2016). "Expression levels of DSCAM1-AS1, CCAT1, MALAT1, MAFG-DT, and UCA1 were increased in ovarian tumors but were not markedly different from the normal tissue group." (PMID 35453574, 2022).
abortion (4 papers, 2019 to 2025). the ending of pregnancy by removing a fetus or embryo before it can survive outside the uterus. "Our previous research also found that MALAT1 polymorphism is associated with susceptibility to recurrent spontaneous abortion." (PMID 31636654, 2019). "The genetic polymorphisms of HULC and MALAT1 are associated with susceptibility to recurrent spontaneous abortion." (PMID 31636654, 2019). "In summary, in this study, we constructed an Nomogram prediction model for recurrent spontaneous abortion based on the expressions of MALAT1, miR-515-5p, and MCL1 mRNA, and verified its clinical application value." (PMID 41480526, 2025). "A recent study conducted by our research group confirmed that polymorphisms in the lncRNAs MALAT1 and CCAT2, which are involved in the regulation of immunity and cell motility, are associated with susceptibility to recurrent spontaneous abortion." (PMID 31636654, 2019).
benign prostatic hyperplasia (4 papers, 2014 to 2021). A non-cancerous nodular enlargement of the prostate gland. "We then evaluated the expression levels of lncRNA PCA3 and MALAT1 (metastasis-associated lung adenocarcinoma transcript 1) in a large cohort of PCa and BPH (benign prostatic hyperplasia) participants." (PMID 34439239, 2021).
bladder transitional cell carcinoma (4 papers, 2020 to 2022). The most common morphologic subtype of urinary bladder carcinoma (over 90% of cases). "There is significant negative correlation between metastasis-associated lung adenocarcinoma transcript 1 (MALAT1) and miR-124 in bladder transitional cell carcinoma tissues and normal mucosa samples." (PMID 34422802, 2021). "Foxq1, putative target gene of miR-124, is positively correlated with the expression of MALAT1 in bladder transitional cell carcinoma." (PMID 34422802, 2021).
choriocarcinoma (4 papers, 2019 to 2025). An aggressive malignant tumor arising from trophoblastic cells. "FBXW8 has been identified as a direct target of miR-218 and is implicated in MALAT1-mediated promotion of choriocarcinoma cell proliferation." (PMID 40534867, 2025). "MALAT1 may also represent a possible diagnostic biomarker for VSCCs and choriocarcinoma, but the studies about their incidence mechanisms are limited." (PMID 34885213, 2021). "What is more, FBXW8 was found to be a direct target of miR-218 and was involved in MALAT1-meidiated promotion of cell proliferation in choriocarcinoma." (PMID 35928868, 2022). "On the other hand, miR-218-5p has been reported to interact with lnc-MALAT1, participating in choriocarcinoma growth." (PMID 30699189, 2019). "Thus, MALAT1 enhances cell proliferation by interacting with miR-218 and upregulating FBXW8, highlighting a critical regulatory axis in choriocarcinoma progression." (PMID 40534867, 2025). "Hence, MALAT1 promoted cell proliferation via interaction with miR-218 and upregulation of FBXW8 in choriocarcinoma." (PMID 35928868, 2022).
Ewing sarcoma (4 papers, 2019 to 2024). A small round cell tumor that lacks morphologic, immunohistochemical, and electron microscopic evidence of neuroectodermal differentiation. "TNC has also been proposed to promote tumor progression by inducing integrin α5β1-mediated YAP activation and upregulating metastasis-associated lung adenocarcinoma transcript 1 (MALAT1) in Ewings sarcoma." (PMID 36102918, 2022). "Interestingly, c-MYC was also reported to transcriptionally activated MALAT1 by binding to MALAT1 promoter, which contributes to a novel SYK/c-MYC/MALAT1 pathway to promote Ewing Sarcoma." (PMID 30683916, 2019).
fibrosis (4 papers, 2019 to 2023). the formation of excess fibrous connective tissue in an organ or tissue in a reparative or reactive process. "MALAT1 was found to be associated with inflammation and apoptosis processes, whereas Kcnq1ot1 association was identified with pyroptosis, cardiac fibrosis, and inflammation." (PMID 33639953, 2021). "In addition, liver MALAT1, in Sookoian’s study, was associated with fibrosis, as evidenced by a greater abundance of MALAT1 in patients with fibrosis (F1–F4) than in those without it (F0)." (PMID 36979495, 2023). "Recent research has proved an important role of MALAT1 in the pathophysiological conditions, tumor progression, inflammation, liver fibrosis, and diabetic complications." (PMID 31684190, 2019). "The level of lnc-MALAT1 is 0.8589 (± 2.3145) in fibrosis group and 0.0887 (± 0.1299)." (PMID 35237178, 2022). "Detection by qRT-PCR showed that relative expression of plasma EVs-Lnc-MALAT1 was 0.089, 0.208, and 2.068 in the control, the low fibrosis and the high fibrosis patients, respectively, showing that relative expression of plasma EVs-Lnc-MALAT1 was correlated with liver fibrogenesis." (PMID 35237178, 2022).
Glucose intolerance (4 papers, 2016 to 2024). Glucose intolerance (GI) can be defined as dysglycemia that comprises both prediabetes and diabetes. "Based on these findings, Malat1+/+ and Malat1-/- mouse littermates were thus probed to detect whether loss of Malat1 would impact age or diet-induced gain in fat mass and development of glucose intolerance." (PMID 29746487, 2018). "Based on the finding of a reduction of Malat1 levels in adipose tissue upon aging, we hypothesized that the loss of Malat1 would impact age or diet-induced gain in fat mass and development of glucose intolerance." (PMID 29746487, 2018). "Furthermore, liver-specific MALAT1 knockdown by tail vein injection of si-MALAT1 daily for 10 days decreased blood glucose level, improved glucose intolerance, increased insulin sensitivity and decreased lipid accumulation in the liver of ob/ob mice." (PMID 36555704, 2022).
hypopharyngeal carcinoma (4 papers, 2018 to 2025). Carcinoma, predominantly squamous cell, arising from the epithelial cells of the hypopharynx. "Both univariate and multivariate analyses indicated that lncRNA MALAT1 is a high-risk factor for hypopharyngeal cancer survival." (PMID 39319867, 2025). "Consistent with the RT-PCR results, RNAscope also showed that lncRNA MALAT1 was significantly overexpressed in hypopharyngeal cancer tissues." (PMID 39319867, 2025). "And more patients will be observed to unravel the clinical significance of MALAT1 in laryngeal and hypopharyngeal carcinoma." (PMID 31792655, 2020). "Taken together, we identified lncRNA MALAT1 as a novel prognostic biomarker for laryngeal and hypopharyngeal cancer." (PMID 31792655, 2020). "In summary, our deactivation model of MALAT1 disentangled the active function of it as a regulator of gene expression governing the hallmarks of laryngeal and hypopharyngeal cancer." (PMID 31792655, 2020). "In this study, we detect the expression of MALAT1 in laryngeal squamous cell carcinoma and hypopharyngeal cancer." (PMID 31792655, 2020). "In this study, the impact of MALAT-1 on laryngeal and hypopharyngeal cancer cell growth and proliferation was confirmed by RNA interference." (PMID 31792655, 2020). "Furthermore, we found that lncRNA MALAT1 was significantly overexpressed in hypopharyngeal cancer tissues, and patients with higher MALAT1 expression had a significantly worse prognosis." (PMID 39319867, 2025). "MALAT1 was significantly up-regulated in laryngeal and hypopharyngeal carcinoma cells." (PMID 31792655, 2020). "Cell cycle analysis, Cell Counting Kit-8 assay, Transwell assay, quantitative reverse transcription PCR, and wound-healing assays were performed to evaluate the impact of MALAT1 depletion on laryngeal or hypopharyngeal cancer cell’s growth, proliferation, apoptosis, invasion and migration." (PMID 31792655, 2020). "In addition, we probed the function of MALAT1 in the development of laryngeal and hypopharyngeal cancer by developing a MALAT1 silencing model in human laryngeal tumor cells." (PMID 31792655, 2020). "Although our result shows that MALAT1 may act as a regulator of gene expression governing hallmarks of laryngeal and hypopharyngeal cancer, it is only one component in this comprehensive process and may carry out its role by working in coordination with other molecules and through a complex network." (PMID 31792655, 2020).
malaria (4 papers, 2020 to 2023). Malaria is a serious and sometimes fatal disease caused by a parasite that commonly infects a certain type of mosquito which feeds on humans. "For example, MALAT1 knockdown in mice was associated with enhanced clearance of visceral leishmaniasis but more severe disease in a model of malaria." (PMID 37079384, 2023). "We uncover the functional significance of Malat1 in the context of two major parasitic infectious diseases, malaria and visceral leishmaniasis, providing new insight into molecular determinants of disease susceptibility." (PMID 32321759, 2020). "Furthermore, some ncRNAs have emerged as potential therapeutic targets, some of which include lncRNAs NEAT1, NEAT2 and lnr6RNA, 152742 in tuberculosis; MALAT1, HEAL, SAF, lincRNA-p21, NEAT1, GAS5, NRON, LINC00173 in HIV/AIDS; miRNA-146a in malaria." (PMID 34737736, 2021).
meningioma (4 papers, 2020 to 2023). A generally slow growing tumor attached to the dura mater. "For instance, the rs619586 A > G polymorphism of MALAT1 has been shown to affect expression levels of MALAT1 and COL5A1, resulting in lower invasiveness of meningioma." (PMID 34885097, 2021). "In this study, we studied the effect of rs619586 on the signalling pathway of MALAT1/miR‐145/COL5A1 and investigated the association between rs619586 polymorphism and the invasiveness of meningioma." (PMID 32720739, 2020). "In this study, we confirmed a regulatory relationship between MALAT1 and miR‐145 in meningioma cells using a luciferase reporter assay." (PMID 32720739, 2020). "In particular, with the presence of rs619586 A>G polymorphism, the expression of MALAT1 and COL5A1 was both reduced, leading to reduced invasiveness of meningioma." (PMID 32720739, 2020).
metabolic syndrome (4 papers, 2019 to 2024). A cluster of metabolic risk factors for CARDIOVASCULAR DISEASES and TYPE 2 DIABETES MELLITUS. "Many other signaling pathways have also shown links to MALAT1 and the metabolic syndrome." (PMID 39502508, 2024).
metastatic prostate carcinoma (4 papers, 2015 to 2023). A carcinoma that arises from the prostate gland and has spread to other anatomic sites. "A total of 163 transcripts comprising 161 genes, a pseudogene (RPL32P3), and an oncogenic lncRNA (MALAT1) were found to be significantly elevated in patients with metastatic prostate cancer compared with localized cases." (PMID 37812088, 2023). "Choline kinase alpha (CHKA), an essential gene in phospholipid metabolism, is among the modulated MALAT1-targeted transcripts in advanced and metastatic prostate cancer (PCa)." (PMID 35740569, 2022). "Co-cultures of PC3 cells with SostKO and WT osteoblasts revealed lncRNA MALAT1 as one of the most highly up-regulated transcripts in PC3 cells co-cultured with SostKO osteoblasts, an RNA we also found elevated in clinical samples of metastatic prostate cancer." (PMID 27600237, 2015).
myocardial inflammation (4 papers, 2020 to 2023). "In a myocarditis model, cardiac innate immunity is partly mediated by lncRNA metastasis-associated lung adenocarcinoma transcript 1 (MALAT1)." (PMID 37025175, 2023). "Metastasis-associated lung adenocarcinoma transcript 1 (MALAT1) is involved in cardiac innate immunity in a myocarditis model, and the expression of MMP9 was decreased in MALAT1-deficient bone marrow-derived macrophages." (PMID 35842645, 2022).
oral cancer (4 papers, 2015 to 2025). "Adjusted odds ratios (AORs) and 95% confidence intervals (CIs) of clinical statuses associated with genotypic frequencies of MALAT1 rs619586 in male oral cancer patients who chewed betel nuts (N=1007)." (PMID 34268119, 2021). "Adjusted odds ratios (AORs) and 95% confidence intervals (CIs) of clinical statuses associated with genotypic frequencies of MALAT1 rs3200401 in male oral cancer patients who chewed betel nuts (N=1007)." (PMID 34268119, 2021). "Odds ratio (OR) and 95% confidence interval (CI) of oral cancer associated with MALAT1 genotypic frequencies." (PMID 34268119, 2021). "Adjusted odds ratios (AORs) and 95% confidence intervals (CIs) of clinical statuses associated with genotypic frequencies of MALAT1 rs619586 in male oral cancer patients (N=1350)." (PMID 34268119, 2021). "Adjusted odds ratios (AORs) and 95% confidence intervals (CIs) of clinical statuses associated with genotypic frequencies of MALAT1 rs3200401 in male oral cancer patients (N=1350)." (PMID 34268119, 2021). "Moreover, ongoing clinical trials explore the potential of EGFR-AS1 and its target EGFR gene, as well as MALAT1 and its target miR-124, as biomarkers and innovative therapeutic targets in oral cancer." (PMID 39941858, 2025). "Adjusted odds ratios (AORs) and 95% confidence intervals (CIs) of clinical statuses associated with genotypic frequencies of MALAT1 rs3200401 in male oral cancer patients who did not chew betel nuts (N=343)." (PMID 34268119, 2021). "Further investigation into the molecular mechanism underlying dysregulation of MALAT1 expression in OSCC cells will help to better understand tumor progression of OSCC, identify candidate biomarkers for OSCC prognosis, and guide the development of therapeutic targets for oral cancer." (PMID 26522444, 2015).